CCDC28B (coiled-coil domain containing 28B)
Description:
Involved in ciliogenesis. Regulates cilia length through its interaction with MAPKAP1/SIN1 but independently of mTORC2 complex. Modulates mTORC2 complex assembly and function, possibly enhances AKT1 phosphorylation. Does not seem to modulate assembly and function of mTORC1 complex.
Synonyms: MGC1203; RP4-622L5.5; LTAP2B
Tractability: PROTAC: ubiquitination databases record sites on it; its protein half-life has been measured.
Gene: Protein-coding gene on chromosome 1 (32,200,383 to 32,205,453, forward strand). Ensembl gene ENSG00000160050.
Subcellular location: Cytoplasm, cytoskeleton, microtubule organizing center, centrosome
Gene Ontology:
Molecular function: protein binding
Biological process: cilium assembly
Cellular component: centrosome
Genetic constraint (gnomAD): Loss-of-function variants: 17 observed, 18.78 expected, observed/expected ratio (o/e) 0.91, 90% interval 0.62 to 1.36. The upper end of that interval is the gene's LOEUF score, 1.36, which puts it in group 5 of 6, group 1 being the genes least tolerant of losing a copy. Missense variants: 213 observed, 241.22 expected, observed/expected ratio (o/e) 0.88, 90% interval 0.79 to 0.99. Synonymous variants: 116 observed, 102.78 expected, observed/expected ratio (o/e) 1.13, 90% interval 0.97 to 1.32.
Homologues: Orthologues: macaque CCDC28B (99% identical), dog CCDC28B (97% identical), rat Ccdc28b (97% identical), mouse Ccdc28b (96% identical), guinea pig CCDC28B (96% identical), pig CCDC28B (96% identical), rabbit CCDC28B (96% identical), chimpanzee CCDC28B (92% identical), tropical clawed frog ccdc28b (61% identical), zebrafish ccdc28b (60% identical), Drosophila melanogaster CG10874 (34% identical). Paralogues in human: CCDC28A (49% identical).
Diseases named in the same sentence as CCDC28B in open-access papers:
CCDC28B is named in the same sentence as 23 diseases in open-access papers, as found by Europe PMC text mining. Sharing a sentence is not in itself a finding about the gene and the disease. The quoted sentences say what the papers report.
Bardet-Biedl syndrome (9 papers, 2018 to 2024). A ciliopathy with multisystem involvement. "Ccdc28b functions in ciliogenesis and is associated with Bardet–Biedl syndrome, a syndrome linked to vision loss, obesity, speech impairment, and intellectual disability." (PMID 34794440, 2021). "CCDC28B encoded protein is Coiled-Coil Domain Containing 28B, one of Bardet–Biedl syndrome-related proteins." (PMID 34638726, 2021). "The protein encoded by the Ccdc28b gene (coiled coil domain-containing 28B) is involved in ciliogenesis and exerts a modifier effect on Bardet–Biedl syndrome." (PMID 32429546, 2020). "In humans, CCDC28B mutations are associated with Bardet-Biedl syndrome (BBS), a pleiotropic genetic disease caused by impaired primary cilia functions." (PMID 39500989, 2024). "CCDC28B (coiled-coil domain-containing protein 28B) was identified as a modifier in the ciliopathy Bardet-Biedl syndrome (BBS)." (PMID 35653384, 2022). "One example of evidence of such modifiers was the report demonstrating that a 430C to T transition in MGC1203 gene (a pericentriolar protein CCDC28B that interacts with several Bardet–Biedl syndrome, BBS proteins) has an epistatic effect on BBS patients." (PMID 34211969, 2021). "Furthermore, genetic interaction studies suggest that the nuclear/cytoplasmic distribution of CCDC28B, a protein associated with Bardet-Biedl syndrome, is influenced by KIF5B, as targeting KIF5B leads to nuclear accumulation of CCDC28B." (PMID 38218748, 2024). "CCDC28B was originally identified as a second site modifier of the ciliopathy Bardet-Biedl syndrome (BBS, OMIM: 209900) although its contribution is likely variable among cohorts." (PMID 29445114, 2018).
Obesity (4 papers, 2019 to 2023). Accumulation of substantial excess body fat. "Thus, it will be interesting to study whether variants in genes such as CCDC28B could contribute to modulating the presentation of obesity in BBS." (PMID 35653384, 2022). "Ccdc28b mut animals i) do not present clear structural cilia affectation, although we did observe mild defects in cilia density and cilia length in some tissues, ii) reproduce normally, and iii) do not develop retinal degeneration or obesity, two hallmark features of reported BBS murine models." (PMID 35653384, 2022). "Overall, our results show that Ccdc28b mut animals do not present hyperphagia or obesity but show a mild phenotype related to systemic glucose management." (PMID 35653384, 2022). "Overall, our data indicate that targeting Ccdc28b in the mouse is not sufficient to cause a strong ciliary defect and accordingly, does not cause phenotypes that are highly penetrant in different mouse BBS models, such as retinal degeneration or obesity." (PMID 35653384, 2022).
ciliopathies (2 papers, 2020 to 2022). "In this work, we generated a Ccdc28b mutant mouse to determine whether abrogating Ccdc28b function would be sufficient to cause a ciliopathy phenotype in mammals, and to generate a tool to continue dissecting its modifying role in the context of BBS." (PMID 35653384, 2022). "However, the data also raised the question of whether other types of mutations (i.e. null mutations) in CCDC28B could be sufficient to cause a ciliopathy." (PMID 35653384, 2022).
Hypertension (2 papers, 2020 to 2023). The presence of chronic increased pressure in the systemic arterial system. "Among them, SNPs in genes Ephx1, Pla2r1, and Ccdc28b were identified as candidates responsible for the concomitant manifestation of hypertension and signs of accelerated aging in OXYS rats." (PMID 32429546, 2020). "So far, genes Pla2r1 and Ccdc28b are not yet associated with hypertension; however, according to our results, they hold promise for further research into their role in the hypertensive state in OXYS rats and in many other rat strains modeling hypertension." (PMID 32429546, 2020).
autism (1 paper, 2022). Persistent deficits in social interaction and communication and interaction as well as a markedly restricted repertoire of activity and interest as well as repetitive patterns of behavior. "In addition, one de novo mutation and several inherited missense variants in CCDC28B have been reported in the Simons Simplex autism cohort." (PMID 35653384, 2022).
breast carcinoma (1 paper, 2024). "The results showed that 5 genes, APOA5, CCDC28B, CCL5, SERPINA12, and WT1, were significantly overexpressed in breast cancer patients (P < 0.05)." (PMID 38676834, 2024). "For example, the role of the gene CCDC28B has been confirmed in gastric cancer, but its role in breast cancer has not been discovered." (PMID 38676834, 2024).
diabetes mellitus (1 paper, 2023). A metabolic disorder characterized by abnormally high blood sugar levels due to diminished production of insulin or insulin resistance/desensitization. "Ten potential target genes were identified, out of which three common potential target genes (CCDC28b, PDCD6IP, and USP34) were selected, which are most effective for cardiovascular diseases, diabetes mellitus, IBD, and PCOS." (PMID 38283897, 2023).
gastric cancer (1 paper, 2024). A primary or metastatic malignant neoplasm involving the stomach. "It was worth mentioned that we also discovered the gene CCDC28B, which may play an important role in gastric cancer development." (PMID 38676834, 2024).
mental disorder (1 paper, 2020). A disease that has its basis in the disruption of mental process. "In addition, the Pla2r1 gene is known to be associated with mental disorders, and Ccdc28b is related to retinal dystrophy." (PMID 32429546, 2020).
sialadenitis (1 paper, 2013). Sialadenitis is an infection of the salivary glands. "A difference in Zbtb8a and Ccdc28b expression between the NOD and B10 alleles was previously reported in the salivary glands in a model of sialadenitis." (PMID 23934554, 2013).
tumor (2 papers, 2016 to 2021). "Among them, we selected five decreased (CCDC28B, SREK1IP1/P18SRP/SFRS12IP1, RASL10B, PHF21A/BHC80 and PGC) and two increased genes (IL-11 and CXCL2), by microarray, as differentiation-, splicing-, inflammation-, or tumor-related genes." (PMID 26701885, 2016).
cancer (1 paper, 2024). A tumor composed of atypical neoplastic, often pleomorphic cells that invade other tissues. "Among them, CCDC28B showed strong positive and negative staining contrast in cancer cells, CCL5 exhibited moderate positive and negative staining contrast in cancer cells, and WT1 showed weak positive and negative staining contrast in cancer cells." (PMID 38676834, 2024). "Moreover, ADRB1, CCDC28B, MRAP2, SERPINA12, and WT1 were able to effectively distinguish between normal breast tissue and cancer tissue (AUC > 0.6)." (PMID 38676834, 2024).
cardiovascular diseases (1 paper, 2023). "The GO analysis for CCDC28b show heart looping, heart morphogenesis, and heart development related to cardiovascular diseases." (PMID 38283897, 2023).
CCDC28B also shares sentences with these, for which no sentence is quoted: Anxiety (1 paper); cerebrovascular disorder (1); hepatocellular carcinoma (1); Intellectual disability (1); Meckel-Gruber syndrome (1); retinal degeneration (1); Retinal dystrophy (1); retinitis pigmentosa (1); retinopathy (1); Stroke (1).